TPD52L1 (TPD52 like 1)
Synonyms: hD53; D53; TPD53
Tractability: Antibody: the Human Protein Atlas places it where antibodies can reach. PROTAC: ubiquitination databases record sites on it; its protein half-life has been measured.
Gene: Protein-coding gene on chromosome 6 (125,119,049 to 125,264,407, forward strand). Ensembl gene ENSG00000111907.
Subcellular location (Human Protein Atlas): Cell Junctions; Cytosol; Plasma membrane
Pathways (Reactome):
Vesicle-mediated transport: Golgi Associated Vesicle Biogenesis
Gene Ontology:
Molecular function: identical protein binding; protein binding; protein homodimerization activity
Biological process: G2/M transition of mitotic cell cycle; positive regulation of apoptotic signaling pathway; positive regulation of JNK cascade; positive regulation of MAP kinase activity
Cellular component: cytoplasm; perinuclear region of cytoplasm
Genetic constraint (gnomAD): Loss-of-function variants: 14 observed, 22.39 expected, observed/expected ratio (o/e) 0.63, 90% interval 0.41 to 0.98. The upper end of that interval is the gene's LOEUF score, 0.98, which puts it in group 4 of 6, group 1 being the genes least tolerant of losing a copy. Missense variants: 188 observed, 247.81 expected, observed/expected ratio (o/e) 0.76, 90% interval 0.67 to 0.86. Synonymous variants: 73 observed, 87.42 expected, observed/expected ratio (o/e) 0.84, 90% interval 0.69 to 1.01.
Homologues: Orthologues: chimpanzee TPD52L1 (99% identical), macaque TPD52L1 (99% identical), rabbit TPD52L1 (93% identical), dog TPD52L1 (93% identical), mouse Tpd52l1 (91% identical), pig TPD52L1 (91% identical), rat Tpd52l1 (90% identical), guinea pig TPD52L1 (86% identical), tropical clawed frog tpd52l1 (71% identical), zebrafish tpd52l1 (55% identical), Caenorhabditis elegans F13E6.1 (28% identical), Drosophila melanogaster CG5174 (28% identical). Paralogues in human: TPD52 (55% identical), TPD52L2 (43% identical), TPD52L3 (26% identical).
Diseases named in the same sentence as TPD52L1 in open-access papers:
TPD52L1 is named in the same sentence as 20 diseases in open-access papers, as found by Europe PMC text mining. Sharing a sentence is not in itself a finding about the gene and the disease. The quoted sentences say what the papers report.
breast carcinoma (3 papers, 2021 to 2025). "Significantly high TPD52L1 transcript levels (p = 0.007) in primary breast cancers at the time of surgical removal is a potential biomarker of lymph node metastasis." (PMID 34458146, 2021). "The proteomic dataset showed the elevated expression of tumour protein D53 (hD53 encoded by TPD52L1) and tumour protein D54 (hD54 encoded by TPD52L2) of MCF-7 breast cancer cells in response to the change of extracellular zinc, which explains to some extent why zinc promotes breast cancer growth." (PMID 38249992, 2024).
colon cancer (2 papers, 2021 to 2025). "Among the genes in these patterns, TPD52L1 was further screened as a poor prognostic marker in colon cancer that is associated with a low overall survival (OS) rate (p = 0.001), high recurrence rate (p = 0.0032), and a partial response to current therapeutic regimens." (PMID 34458146, 2021). "We next analyzed whether TPD52L1 is associated with the TNM stages of colon cancer." (PMID 34458146, 2021). "Furthermore, TPD52L1 expression levels affect the malignant behavior of colon cancer cell lines by binding to its partners." (PMID 34458146, 2021).
prostate carcinoma (2 papers, 2021 to 2024). A carcinoma that arises from epithelial cells of the prostate gland. "Other family members, such as TPD53 (also known as TPD52L1), TPD54 (TPD52L2), and TPD55 (TPD52L3), have been reported to be highly expressed in ovary, testis, colon, and prostate cancer, as well as in brain tumors, lymphoma, and leukemias." (PMID 34217360, 2021).
hepatocellular carcinoma (1 paper, 2021). A malignant tumor that arises from hepatocytes. "In a hepatocellular carcinoma study, TPD52L1 was one of eight mRNA biomarkers identified as independent risk factors and was used to develop a prognostic model of OS." (PMID 34458146, 2021).
Insulin resistance (1 paper, 2019). Increased resistance towards insulin, that is, diminished effectiveness of insulin in reducing blood glucose levels. "Tumor protein D52-like 1 (TPD52L1), OLFML1, and MUC1 are novel biomarkers for the development of insulin resistance." (PMID 30678306, 2019).
lung carcinoma (1 paper, 2024). "It has been reported that Cd14 and Tpd52l1 genes are up-regulated in primary lung cancer compared to the adjacent normal tissue." (PMID 38678138, 2024).
nasopharyngeal carcinoma (1 paper, 2021). A carcinoma arising from the nasopharyngeal epithelium. "TPD52L1 is downregulated in post-chemotherapy ovarian tumors and in recurrent nasopharyngeal cancer after the first course of radiotherapy, suggesting that TPD52L1 expression is associated with tumor recurrence and responses to current therapeutic drugs against CRC." (PMID 34458146, 2021).
ulcerative colitis (1 paper, 2021). An inflammatory bowel disease involving the mucosal surface of the large intestine and rectum. "Ulcerative colitis (UC) increases the risk for CRC, and TPD52L1 expression increases progressively from controls, to nondysplastic UC, to UC with neoplasia." (PMID 34458146, 2021).
cancer (9 papers, 2017 to 2024). A tumor composed of atypical neoplastic, often pleomorphic cells that invade other tissues. "The expression level of TPD52L1 in tumor tissues has clinical significance as a marker of poor prognosis and relapse, as well as implications regarding the efficacy of anti-cancer drugs." (PMID 34458146, 2021). "In addition, overexpression of some genes, including ABCB1, TPD52L1, HNRNPR and MICAL3, is associated with poor prognosis in various cancers." (PMID 39682186, 2024). "The involvement of TPD52L1 in various cancers was reported previously." (PMID 34458146, 2021). "The sequential genes upregulated during the progression from cancer stage 1 to 4 are CALB1, TPD52L1 and ITGB8." (PMID 39149248, 2024). "Tumor protein D52-like 1 (TPD52L1) belongs to the TPD52 family; previous research has shown that TPD52 can act as a novel regulator of LKB1-AMPK pathway by negatively regulating AMPK activity and thus affecting cancer cell metabolism." (PMID 39568815, 2024).
tumor (5 papers, 2017 to 2024). "Clinical information from TCGA showed that high TPD52L1 expression was associated with poor prognosis, a higher probability of tumor relapse, and a partial response to current therapeutic regimens." (PMID 34458146, 2021). "Consistently, TPD52L1 downregulation inhibited tumor-associated behaviors." (PMID 34458146, 2021). "The TPD52L1 gene was identified as a potential marker to track tumor formation in CRC and as an indicator of poor patient prognosis." (PMID 34458146, 2021). "The pathways of the interacting proteins may help to clarify the mechanism of TPD52L1 in tumor formation." (PMID 34458146, 2021). "It is possible that TPD52L1 promotes tumor development by interaction with the 14-3-3γ protein." (PMID 34458146, 2021). "Taken together, these findings indicate that the TPD52L1 gene is continuously and monotonically upregulated during tumor formation and highly associated with the non-normal phenotype, suggesting a potential role in tumor formation." (PMID 34458146, 2021). "TPD52L1 was highly negatively correlated (−0.81) with DEGs in the purple module, which are associated with normal tissues, suggesting that TPD52L1 is a potential marker of non-normal phenotypes involved in tumor formation." (PMID 34458146, 2021).
TPD52L1 also shares sentences with these, for which no sentence is quoted: brain tumors (1 paper); leukemia (1); liver cancer (1); lung squamous cell carcinoma (1); lymph node metastasis (1); lymphoma (1); Oral Squamous Cell Carcinoma (1); osteosarcoma (1); ovarian tumors (1); viral infections (1).